OR13A1 (olfactory receptor family 13 subfamily A member 1)
Description:
Odorant receptor.
Tractability: Antibody: UniProt places it where antibodies can reach, with medium confidence; UniProt predicts a signal peptide or a membrane-spanning region; its Gene Ontology location is reachable by antibodies, with medium confidence.
Gene: Protein-coding gene on chromosome 10 (45,302,298 to 45,315,608, reverse strand). Ensembl gene ENSG00000256574.
Subcellular location: Cell membrane
Pathways (Reactome):
Sensory Perception: Expression and translocation of olfactory receptors
Gene Ontology:
Molecular function: odorant binding; olfactory receptor activity; G protein-coupled receptor activity
Biological process: sensory perception of smell; detection of chemical stimulus involved in sensory perception of smell; G protein-coupled receptor signaling pathway
Cellular component: plasma membrane; membrane
Genetic constraint (gnomAD): Loss-of-function variants: 13 observed, 9.68 expected, observed/expected ratio (o/e) 1.34, 90% interval 0.86 to 1.88. That is too few expected variants to judge how well the gene tolerates losing a copy. Missense variants: 509 observed, 441.53 expected, observed/expected ratio (o/e) 1.15, 90% interval 1.07 to 1.24. Synonymous variants: 238 observed, 186.19 expected, observed/expected ratio (o/e) 1.28, 90% interval 1.15 to 1.42.
Homologues: Orthologues: chimpanzee OR13A1 (97% identical), macaque OR13A1 (93% identical), dog OR13A1 (85% identical), pig OR13A1 (80% identical), mouse Or13a1 (80% identical), rat Or13a1 (78% identical), tropical clawed frog or5ar35b (43% identical), tropical clawed frog or5ar33 (41% identical). Paralogues in human: OR8A1 (44% identical), OR5AN1 (42% identical), OR8B3 (42% identical), OR9H1 (42% identical), OR5I1 (42% identical), OR8B2 (42% identical), OR8D4 (42% identical), OR9G4 (42% identical), OR5AP2 (41% identical), OR8G1 (41% identical), OR5A1 (41% identical), OR5B21 (41% identical), and 84 more.